FGF2 (fibroblast growth factor 2)
Diseases named in the same sentence as FGF2 in open-access papers (continued):
Sharing a sentence is not in itself a finding about the gene and the disease.
pituitary tumor (6 papers, 2007 to 2023). A benign or malignant neoplasm affecting the pituitary gland. "Numerous studies have reported that FGF-2 is important in pituitary tumor development." (PMID 37958474, 2023). "Furthermore, FGFR1 has been proposed as a candidate marker of pituitary tumors together with FGF2 and pituitary tumor transforming gene (PTTG); indeed, the FGF2 receptor FGFR1 was found to be highly expressed in pituitary tumors compared to the normal gland." (PMID 25505910, 2014). "Likewise, PTTG stimulates fibroblast growth factor 2 (FGF2) and vascular endothelial growth factor (VEGF) production, accelerates tissue angiogenesis, and facilitates pituitary tumor progression through local invasion of the surrounding tissues." (PMID 29104246, 2017). "Taken together these results suggest that angiogenesis of pituitary tumors in the Drd2−/− mice does not depend on FGF-2 and PTTG expression." (PMID 25505910, 2014). "In this regard, pro- and antiangiogenic growth factors, such as FGF-2, VEGF, and others, may determine the final angiogenic phenotype of pituitary tumors and thus subsequent tumor behavior." (PMID 25505910, 2014).
pterygium (6 papers, 2007 to 2022). A wedge-shaped fibrovascular lesion arising from the bulbar conjunctiva and extending to the cornea. "It has been demonstrated that FGF-2 can induce inflammation and angiogenesis in pterygium by stimulating the expression of cyclooxygenase-2 (COX-2)." (PMID 36278670, 2022). "FGF-2 mRNA levels were found to be higher in pterygium and normal conjunctiva." (PMID 36278670, 2022). "Results support the involvement of FGF2 and VEGFA in pterygium pathogenesis and imply that pharmacological modification of the clinical behavior of pterygium may be possible with agents directed against specific growth factors, such as VEGFA." (PMID 23432803, 2013). "Furthermore, FGF2 and VEGFA expression was significantly higher in more advanced pterygium, compared with less advanced ones, whereas VEGFA was also significantly correlated with postoperative recurrence." (PMID 23432803, 2013).
sarcopenia (6 papers, 2017 to 2024). Progressive decline in muscle mass due to aging which results in decreased functional capacity of muscles. "Further studies are needed to confirm the results of our study and explore the underlying mechanism for the association of FGF2 DNA methylation with sarcopenia." (PMID 38641928, 2024). "Further loss‐ and gain‐of‐function experiments of DNMTs or TETs will help to explore the exact mechanisms by which causes the hypomethylation of FGF2 in sarcopenia." (PMID 38641928, 2024). "Moreover, older adults with lower levels of FGF2_30 methylation (<0.15) had more than 9‐fold risk of sarcopenia when compared to those with higher FGF2_30 methylation levels." (PMID 38641928, 2024). "Our results demonstrated that DMR in FGF2 was correlated with the risk and severity of sarcopenia." (PMID 38641928, 2024). "Finally, we conclude that knockout of Fgf2 exacerbates age-associated changes in muscle phenotype consistent with sarcopenia likely contributing to impaired muscle function in mice." (PMID 34040128, 2021). "Further studies are needed to investigate the correlation between FGF2_30 methylation status and serum FGF2 level in sarcopenia patients." (PMID 38641928, 2024). "Further in‐depth studies will be needed to elucidate the precise mechanism governing the pathological effect of FGF2 on the development of sarcopenia." (PMID 38641928, 2024). "Subgroup analysis based on the severity of sarcopenia showed that the methylation levels of CXCL12_22, FGF21_59, and FGF2_30 were also significantly different between patients with moderate sarcopenia and those with severe sarcopenia." (PMID 38641928, 2024). "Our results suggest that lower FGF2_30 methylation is correlated with the risk and severity of sarcopenia in the older adults, indicating that FGF2 methylation serve as a surrogate biomarker for the screening and evaluation of sarcopenia." (PMID 38641928, 2024). "Receiver operating characteristic (ROC) curve analysis was used to determine the optimum cut‐off levels of fibroblast growth factor 2 (FGF2)_30 methylation best predicting sarcopenia and area under the ROC curve (AUC) was measured." (PMID 38641928, 2024). "FGF2 plays a critical role in adult regenerative myogenesis; however, the exact role of FGF2 in sarcopenia is undefined." (PMID 38892069, 2024). "Considering that the position of FGF2_30 segment is located in the promoter of FGF2, the observed lower FGF2_30 methylation level in patients with sarcopenia may therefore indicate a potential role of elevated FGF2 in the pathogenesis of sarcopenia." (PMID 38641928, 2024). "Further methylation‐specific PCR identified that methylation of fibroblast growth factor 2 (FGF2)_30 was lower in patients with sarcopenia and the level was decreased as the severity of sarcopenia increased, which was confirmed by pyrosequencing." (PMID 38641928, 2024). "Secondly, although our results suggest lower FGF2_30 methylation might be a potential biomarker for sarcopenia, we did not examine the serum level of FGF2 in patients with sarcopenia." (PMID 38641928, 2024). "Further examination revealed evidence that enhanced FGF2 signaling due to increased 6-O-sulfation (6-O-sufated HS is required for fibroblast growth factor receptor, FGFR, binding and FGF2 signaling) in the aging mice exhausted the quiescent SCs leading to fibrosis and sarcopenia." (PMID 30564580, 2018).
soft tissue sarcoma (6 papers, 2011 to 2025). A malignant neoplasm arising from muscle tissue, adipose tissue, blood vessels, fibrous tissue, or other supportive tissues excluding the bones. "PTX3 has been described as a potent FGF2 inhibitor and has been reported to be down-modulated in different types of cancer, including soft tissue sarcomas in which its absence exerts pro-tumor effects." (PMID 30443492, 2018).
thyroid tumor (6 papers, 2017 to 2024). A benign or malignant neoplasm affecting the thyroid gland. "In thyroid tumors, MALAT1 promotes Fibroblast Growth Factor 2 (FGF2) secretion from tumor-associated macrophages into the tumor microenvironment to mediate angiogenesis." (PMID 34512715, 2021). "FGF1 and FGF2 have been reported as over-expressed in differentiated thyroid tumors, but their receptors present contrasting results." (PMID 28469731, 2017). "Interestingly, PROX1 and FGF2 showed opposing expression levels in FTC tissues and seven thyroid tumor-derived cell lines." (PMID 31717665, 2019).
acute kidney injury (5 papers, 2020 to 2026). Sudden and sustained deterioration of the kidney function characterized by decreased glomerular filtration rate, increased serum creatinine or oliguria. "This study suggests that FGF2 treatment should be considered as a therapeutic strategy for acute kidney injury caused by I/R." (PMID 32266254, 2020).
acute myeloid leukemia (5 papers, 2016 to 2025). Acute myeloid leukemia (AML) is a group of neoplasms arising from precursor cells committed to the myeloid cell-line differentiation. "For example, FGF2 causes chemoresistance in patients suffering from acute myeloid leukemia." (PMID 35433697, 2022). "Since both FGF2 and GPC1 are key components of tumor progression for a wide range of cancer types, we propose that the prominent function of GPC1 in driving efficient unconventional secretion of FGF2 might play a key role for tumor development such as acute myeloid leukemia." (PMID 35348113, 2022).
age-related macular degeneration (5 papers, 2016 to 2026). Age-related loss of vision in the central portion of the retina (macula), secondary to retinal degeneration. "An isolated inhibitory RNA aptamer against FGF2, named RBM-007, has followed an extensive preclinical study, with two clinical trials in phase 2 and phase 1, respectively, underway to assess the therapeutic impact in age-related macular degeneration (wet AMD) and achondroplasia (ACH), respectively." (PMID 34203430, 2021).
chordoma (5 papers, 2011 to 2022). Chordomas are rare malignant tumors arising from embryonic remnants of the notochord in axial skeleton. "Hub genes PDGFRB, KDR, FGF2 and pi3k-akt signaling pathway, Rap1 signaling pathway will become a new target for the future treatment of chordoma." (PMID 32011476, 2020). "The Hub genes PDGFRB, KDR, and FGF2 are involved in the pathogenesis of chordoma via the Pi3k-Akt signaling pathway and the Rap1 signaling pathway." (PMID 32011476, 2020). "It has been reported that FGF2 and TGF-a involve in chordoma recurrence and FGFR/MEK/ERK/TBXT pathway coordinately regulates chordoma cell growth and survival." (PMID 36520826, 2022). "Because connective tissue cells were visible during cultivation, we measured HGF, FGF2, SDF-1, and PDGF compared to stable chordoma cell lines (MUG-Chor118 and U-CH1-319) and healthy normal skin fibroblasts (fibro), as well as tumor-surrounding cancer cells (TSC)." (PMID 27072875, 2016). "FGF2 induces MEK/ERK phosphorylation and upregulates BRACHYURY expression, BRACHYURY knockdown blocks the effects of FGF signaling, suggesting a positive feedback loop between FGF/FGFR and BRACHYURY could be required for chordoma cells' growth and survival." (PMID 32695672, 2020).
chronic lymphocytic leukemia (5 papers, 2013 to 2024). "Moreover, increased FGF-2 immunoreactivity significantly correlates with an increased risk of chronic lymphocytic leukemia (CLL) and, at the same time, with a reduced susceptibility to apoptosis." (PMID 38473833, 2024).
cognitive decline (5 papers, 2022 to 2024). "Our study simultaneously tested a panel of 27 immune markers and showed that IP-10, FGF-2, TGFa and VEGF concentrations in MCI patients were associated with APOE genotype, suggesting their association with cognitive decline in the elderly." (PMID 37686198, 2023). "FGF2 gene transfer reversed hippocampal function and cognitive decline in mouse models." (PMID 39385222, 2024).
cutaneous melanoma (5 papers, 2012 to 2024). A primary melanoma arising from atypical melanocytes in the skin. "Slug regulates invasion and metastasis in cutaneous melanoma through the cooperation of TSP-1 with FGF-2 and VEGF/VEGFR-1." (PMID 35201457, 2021). "ANGPT2 gene expression is significantly higher (P < 0.01) in skin melanoma compared to normal skin, whereas expression of ANGPT1, PDGFA, FGF2, and VEGF‐A is not significantly different." (PMID 34102002, 2021).
emphysema (5 papers, 2006 to 2022). "Intratracheal administration of FGF-2 increases blood flow in damaged lungs and improves blood gas values, thus allowing recovery of pulmonary function in a canine emphysema model." (PMID 30429461, 2018). "The results of this study demonstrate that FGF-2 is involved in the pathogenesis of emphysema; therefore, rFGF-2 is a therapeutic option for Korean patients with emphysema-type COPD." (PMID 30429461, 2018). "Previous studies have suggested that there are beneficial effects of recombinant FGF-2 (rFGF-2) in treating COPD in animal emphysema models." (PMID 30429461, 2018). "In this study, the mechanisms of FGF-2 in the development of COPD (especially emphysema) and the therapeutic potential of FGF2 were explored in a cigarette smoke-exposed C57BL/6 J emphysema mouse model." (PMID 30429461, 2018). "Finally, FGF-2 significantly protected against the development of emphysema induced by short-term exposure to cigarette smoke in mice." (PMID 30429461, 2018). "Consistently, the airway administration of FGF-2, another member of FGF family promoting tissue repair, was reported to reduce emphysema and to enhance lung repair in cigarette smoke-exposed or elastase-induced COPD mouse models, possibly by attenuating inflammation and alveolar cell death." (PMID 36480517, 2022). "The result showed that nanovesicles significantly reduced the emphysema via its cargo content, FGF2, while no significant reduction of emphysema was observed in ASC-derived exosome." (PMID 33436065, 2021).
experimental autoimmune encephalomyelitis (5 papers, 2014 to 2024). An autoimmune demyelinating disease of the central nervous system that is produced experimentally in animals by the injection of homogenized brain or spinal cord in Freund's adjuvant. "Based on a previous report, treatment with FGF2 in animals suffering from experimental autoimmune encephalomyelitis (EAE) reduced the extent of demyelination." (PMID 26464826, 2015). "In experimental autoimmune encephalomyelitis, the animal model of MS, FGF-2 may act as a remyelinating and nerve fiber preserving agent." (PMID 24735639, 2014).
non-Hodgkin lymphoma (5 papers, 2002 to 2020). Distinct from Hodgkin lymphoma both morphologically and biologically, non-Hodgkin lymphoma (NHL) is characterized by the absence of Reed-Sternberg cells, can occur at any age, and usually presents as a localized or generalized lymphadenopathy associated with fever and weight loss. "In addition, elevated levels of FGF2 in serum have been reported for non-Hodgkin lymphoma (NHL) patients with poor prognosis, shortened survival, and higher risk for mortality." (PMID 23988031, 2013).
pancreatic ductal adenocarcinoma (5 papers, 1995 to 2024). An infiltrating adenocarcinoma that arises from the epithelial cells of the pancreas. "A recent study showed that combined treatment of a MAPK inhibitor (Trametinib) and Palbociclib induced senescence and these senescent pancreatic ductal adenocarcinoma cells showed increased secretion of pro‐angiogenic factors (VEGF, PDGFA/B, and FGF2) and MMPs (MMP2/3/7/9/10)." (PMID 37854019, 2024).
pericardial effusion (5 papers, 2012 to 2021). Fluid collection within the pericardial sac, usually due to inflammation. "Thus, a higher level of FGF2 together with other inflammatory cytokines in the serum and pericardium of patients proposes a causative role for FGF2 in the pathogenesis of pericardial effusion." (PMID 34095143, 2021). "Moreover, FGF-2 levels in a pericardial effusion were elevated in patients with inflammatory pericardial effusion, suggesting that FGF-2 participates in the pathogenesis of inflammatory pericardial disease." (PMID 29776409, 2018).
pheochromocytoma (5 papers, 2012 to 2024). "Our data demonstrated that hADMPCs, when exposed to oxidative stress, facilitate neuronal differentiation in rat pheochromocytoma cell line PC12 cells by upregulation of fibroblast growth factor 2 (FGF2) and bone morphogenetic protein 2 (BMP2) secretion through p38 MAPK activation." (PMID 22870983, 2012).
prostate tumor (5 papers, 2014 to 2025). "Moreover, increased mRNA levels and protein expressions of fibroblast growth factor 2 (FGF2) were detected in mast cell-infiltrating prostate tumors." (PMID 29379802, 2017).
retinal diseases (5 papers, 2017 to 2022). "Moreover, analysis of the DARs with enhanced E5 accessibility in the 6hPR + FGF2 RPE revealed genes associated with ECM glycoproteins, actin-based processes, SLC transporters, retinal diseases, and also fetal retina RPE." (PMID 35517508, 2022). "When dividing two major proliferative retinal diseases into simple and exacerbated cases, SOF with exacerbated PDR but not exacerbated PVR demonstrated significantly higher FGF-2 and TGF-β1 levels than simple cases." (PMID 28572674, 2017).
retinitis pigmentosa (5 papers, 2009 to 2026). Retinitis pigmentosa (RP) is an inherited retinal dystrophy leading to progressive loss of the photoreceptors and retinal pigment epithelium and resulting in blindness usually after several decades. "NGF injection rescues photoreceptor degeneration in the RCS rat model of retinitis pigmentosa, involving secondary effects by other neurotrophins such as FGF2 and VEGF." (PMID 19806208, 2009).
retinoblastoma (5 papers, 2012 to 2024). A malignant tumor that originates in the nuclear layer of the retina. "Accordingly, immunofluorescence analysis of human retinoblastoma tissues showed a positive staining for FGF2 located in both tumor and vascular cells." (PMID 35409195, 2022). "Similar results were obtained in a transgenic mouse model of retinoblastoma, where a time-course analysis of FGF2 expression showed a peak of production during the early stages of tumorigenesis, localized in the perivascular area." (PMID 35409195, 2022). "High concentrations of FGF2 have been found in the aqueous humor of patients affected by either retinoblastoma or uveal melanoma." (PMID 35409195, 2022). "In addition, analysis of aqueous humor from retinoblastoma patients revealed higher concentration of FGF2 compared to the control group, thus supporting the hypothesis that FGF may play a role in retinoblastoma progression." (PMID 35409195, 2022). "Uveal melanoma and retinoblastoma are characterized by a severe overexpression of the FGF/FGFR system, especially of the FGF-2 molecule." (PMID 36278670, 2022). "Regarding other ocular neoplasms, scattered evidence obtained on human retinoblastoma cell lines showed the expression of all four FGFRs, with cell proliferation in response to stimulation with FGF1 and FGF2." (PMID 35409195, 2022).
thrombosis (5 papers, 2018 to 2024). "FGF2 expression is enhanced in endothelial precursor cells in deep vein thrombosis, suggesting that FGF2 is pro-thrombotic." (PMID 39199276, 2024). "Interestingly, the levels of IL-1β and FGF-2 together with MCP-1, MIP-1α, and IP-10 were found to be related to thrombosis." (PMID 36012146, 2022).
ZIKV infection (5 papers, 2018 to 2022). "Intriguingly, the mRNA transcript that was most highly induced by ZIKV infection encodes fibroblast growth factor 2 (FGF2-002; folds change (FC) = 8,607), a key cytokine secreted by Sertoli cells that has reported roles in spermatogenesis." (PMID 29615760, 2018). "IPA predicted the up- and downregulation of several immunomodulatory molecules at both timepoints, including FGF2, which is known to support ZIKV infection by suppressing IFN signaling." (PMID 33865073, 2021). "The RNAseq analyses indicated that FGF2 mRNA levels were dramatically induced in Sertoli cells during acute ZIKV infection." (PMID 29615760, 2018). "Additionally, Zika virus infection of human fetal astrocytes elevated expression of FGF2, which suppressed IFN signaling and facilitated Zika virus infection and spread." (PMID 35675358, 2022). "In addition, a dramatic increase in production and secretion of fibroblast growth factor 2 (FGF2) was found to occur during ZIKV infection." (PMID 29615760, 2018). "In addition, as well as being benefiting virus replication, the observed dysregulation of FGF2 during ZIKV infection may have short and/or long-term implications for fertility." (PMID 29615760, 2018).
aneurysm (4 papers, 2017 to 2024). Bulging or ballooning in an area of an artery secondary to arterial wall weakening. "Evidence provided by in vitro and in vivo experimental studies showed that cellular proliferation, tissue fibrosis, and vascular wall thickness were enhanced by FGF-2 in aneurysm models." (PMID 38173028, 2024).